RAC1 (Rac family small GTPase 1)
Diseases named in the same sentence as RAC1 in open-access papers (continued):
Sharing a sentence is not in itself a finding about the gene and the disease.
atrial fibrillation (5 papers, 2012 to 2025). A disorder characterized by an electrocardiographic finding of a supraventricular arrhythmia characterized by the replacement of consistent P waves by rapid oscillations or fibrillatory waves that vary in size, shape and timing and are accompanied by an irregular ventricular response. "Increased atrial oxidative stress has an important role in inducing and maintaining atrial fibrillation (AF), and the activation of the small GTPase Rac1 contributes to the oxidative stress." (PMID 25153633, 2014). "In human atrial tissues, atorvastatin inhibits Rac1-mediated activation of Nox2 NADPH-oxidase, lowers atrial superoxide generation and reduces the risk of atrial fibrillation post-CABG." (PMID 22364136, 2012). "Atrial fibrillation is characterized by increased Rac1-GTPase activity." (PMID 22364136, 2012). "Human left atrial samples from patients with atrial fibrillation (AF) show upregulated Rac1 GTPase activity compared to patients with sinus rhythm, and Rac1ET mice develop AF by 16 months of age." (PMID 41333012, 2025).
Autoimmunity (5 papers, 2013 to 2024). The occurrence of an immune reaction against the organism's own cells or tissues. "Rac-1 is directly implicated in the activation of caspase-1, which is crucial for processing and secretion of the proinflammatory cytokines IL-1β and IL-18, promoting autoimmunity." (PMID 24147031, 2013). "Here, the authors show that nuclear Tiam1 and Rac1 bind to RORγt on the IL-17 promoter, activating its transcription, and that inhibiting Tiam1/Rac1 is beneficial in a mouse model of autoimmunity." (PMID 27725632, 2016). "Here, we show the guanine nucleotide exchange factor, Tiam1, and its cognate Rho-family G protein, Rac1, regulate interleukin (IL)17A transcription and autoimmunity." (PMID 27725632, 2016). "Moreover, RAC1, along with TIAM1, is implicated in interleukin 17A (IL-17A) transcription and has a role in autoimmunity." (PMID 38577601, 2024). "Rac1 is necessary for IL-17A expression and induction of autoimmunity in mice." (PMID 37834058, 2023).
brain injury (5 papers, 2016 to 2024). Acute and chronic (see also brain INJURIES, CHRONIC) injuries to the brain, including the cerebral hemispheres, CEREBELLUM, and brain STEM. "We also determined that the Ras-related C3 botulinum toxin substrate 1 (Rac1)-myosin light chain kinase (MLCK) pathway was involved in P2Y6R-mediated microglial phagocytosis in radiation-induced brain injury." (PMID 26099306, 2016). "Moreover, the authors determined that the Ras-related C3 botulinum toxin substrate 1 (Rac1)-myosin light chain kinase (MLCK) pathway was involved in P2Y6R-mediated microglial phagocytosis in radiation-induced brain injury." (PMID 32630251, 2020). "We showed here that Rac1 and MLCK were involved in P2Y6R-mediated microglial phagocytosis in radiation-induced brain injury." (PMID 26099306, 2016). "The activation of Epac/Rap1 signal pathway has a neuroprotective effect on CI/R-damaged brain through the recovery of blood-brain barrier, while Rap1 inhibitor GGTI298 and Rac1 inhibitor NSC23766 inhibiting Epac pathway can destroy the blood-brain barrier and aggravate brain injury." (PMID 38543171, 2024).
clear cell renal cell carcinoma (5 papers, 2014 to 2025). "One study suggests SAMHD1 expression promotes focal adhesion kinase (FAK) signaling by binding to cortactin, and in turn activated Rac family small GTPase 1 (Rac1)-mediated lamellipodia formation in human clear cell renal cell carcinoma." (PMID 41280104, 2025). "For example, lncRNA NR2F2-AS1 overexpression mediated the upregulation of Rac1 in clear cell renal cell carcinoma." (PMID 34307388, 2021). "Collectively, our data provide evidence that reduction of RhoA signaling by Activin B together with persistent Rac1 activity is a prerequisite for inducing an invasive phenotype in clear cell renal cell carcinoma." (PMID 25343250, 2014).
dilated cardiomyopathy (5 papers, 2016 to 2025). Cardiomyopathy which is characterized by dilation and contractile dysfunction of the left and right ventricles. "Conversely, Zdhhc3 overexpression causes severe dilated cardiomyopathy that is associated with an increase in palmitoylated Rac1 levels, suggesting that both enhancing or disrupting Rac1 palmitoylation at cysteine-178 can have detrimental effects on cardiac adaptation and remodeling." (PMID 41333012, 2025). "Cardiomyocyte-specific overexpression of the Golgi-localized palmitoylating S-acyltransferase enzyme, zDHHC3, resulted in severe dilated cardiomyopathy which coincided with increased palmitoylated and active Rac1 levels." (PMID 41333012, 2025). "For Rac1 it has been shown that its activity is increased in failing myocardium of human patients suffering from dilated cardiomyopathy (DCM) or ischemic cardiomyopathy (ICM)." (PMID 33906663, 2021). "Failing of the myocardium in patients with dilated cardiomyopathy (DCM) and ischemic cardiomyopathy (ICM) is characterized by an upregulation of NADPH oxidase–mediated ROS release associated with increased RAC1 activity." (PMID 34805976, 2021). "We found that Rac1 is a novel substrate of zDHHC3 using an unbiased proteomic approach and that cardiomyocyte-specific transgenic mice overexpressing Zdhhc3, but not an enzymatically dead mutant, develop lethal dilated cardiomyopathy." (PMID 37926281, 2023).
Encephalocele (5 papers, 2019 to 2023). A neural tube defect characterized by sac-like protrusions of the brain and the membranes that cover it through openings in the skull. "Genetic causes can also be shared between NTD subtypes and comorbid malformations; Grhl3Cre deletion of Rac1 can cause abdominal call defects, spina bifida, exencephaly, and/or encephalocele in mice." (PMID 36138850, 2022). "Hence, this Rac1 loss is probably the cause of subsequent disruption of morphogenesis, leading to occipito-parietal encephalocele." (PMID 31628096, 2019). "However, in the Grhl3Cre-Rac1 encephalocele, the basal surface becomes exposed after loss of the surface ectoderm and underlying mesenchyme." (PMID 31628096, 2019). "In addition, encephaloceles are often observed to be associated with other human birth defects, including other NTDs, cleft palate, craniosynostosis, which are similar phenotypes to those observed in mouse models with Gpr161 cKO or Rac1 cKO." (PMID 34887903, 2021). "Future challenges include a focus on Rac1 and the several signalling pathways in which it functions as a possible site of genomic and/or epigenomic changes that may predispose to nonsyndromic encephalocele." (PMID 31628096, 2019). "Tissue-specific knockout of Rac1 can lead to either cranial NTDs (with open neural folds) or encephalocele, in which the neural tube is closed." (PMID 37364051, 2023). "In contrast, Grhl3Cre-Rac1 mutant fetuses with encephalocele had a large midline deficit in bone formation, where all bones except the nasals were severely affected in their medial aspects." (PMID 31628096, 2019). "To further address the developmental origins of encephalocele in Grhl3Cre-Rac1 fetuses, we examined sections through the mid- and hind-brain of earlier stage fetuses, at E13.5, when the encephalocele defect first becomes identifiable." (PMID 31628096, 2019). "At first sight, the Grhl3Cre-Rac1 mouse model seems to depart from both of these typical features of human encephalocele." (PMID 31628096, 2019). "We conclude that Grhl3Cre-mediated recombination and Rac1 knockdown occur specifically in the surface ectoderm, prior to the stage of onset of ectodermal rupture and appearance of the encephalocele lesion at E13.5." (PMID 31628096, 2019). "Hence, in both Rac1 and Grhl2 models, encephalocele definitively arises after neural tube closure is complete." (PMID 37364051, 2023). "A recent publication showed that encephaloceles result from the defective surface ectoderm in a post-neurulation manner along with severe calvarial bone defects at a later embryonic stage in the surface ectoderm specific deletion of Rac1 mouse model." (PMID 34887903, 2021). "Does the Grhl3Cre-Rac1 mouse serve as a model for human encephalocele?" (PMID 31628096, 2019). "The Grhl3Cre-Rac1 mouse model firmly links neural tube closure defects with encephalocele, as both malformation types result from the same gene defect and individual fetuses frequently exhibit both encephalocele and open spina bifida." (PMID 31628096, 2019). "We examined Rac1 expression by in situ hybridisation at E12.5, a day before the encephalocele lesion could be discerned in Grhl3Cre-Rac1 individuals." (PMID 31628096, 2019). "Moreover, the surface ectoderm, which specifically lacks Rac1 in the mutants, showed evidence of rupture at the earliest stages of encephalocele development, suggesting a mechanism of pathogenesis for the brain herniation." (PMID 31628096, 2019). "Moreover, although the single-gene causation of the Grhl3Cre-Rac1 mouse does not model human encephalocele aetiology, it does demonstrate that a single causative factor can produce encephalocele, exencephaly and spina bifida." (PMID 31628096, 2019). "Here, we report a novel mouse model of occipito-parietal encephalocele, in which the small GTPase Rac1 is conditionally ablated in the (non-neural) surface ectoderm." (PMID 31628096, 2019).
Encephalocele (continued). "Histological sections through the head of Grhl3Cre-Rac1 mutants and control fetuses at E17.5 showed that the encephalocele comprised a mass of brain tissue, which lacked the precise internal structure of the control brain." (PMID 31628096, 2019). "We conclude that encephalocele, at least in Grhl3Cre-Rac1 mutants, is neither the result of failure in neural tube closure nor primarily a skull defect." (PMID 31628096, 2019). "Here, we describe a mouse model of encephalocele resulting from conditional deletion of Rac1, a small GTPase of the Rho family, in the non-neural (surface) ectoderm of the embryo and fetus." (PMID 31628096, 2019). "Indeed, a recent study of mouse embryos in which the Rac1 gene was conditionally deleted in the non-neural ectoderm, revealed that exencephaly and encephalocele are alternative cranial outcomes in individual embryos with this genetic alteration." (PMID 36897404, 2023). "Hence, although almost all mouse mutants lacking Rac1 expression in the surface ectoderm failed in spinal neural tube closure, they had approximately equal frequencies of three distinct cranial phenotypes: exencephaly, occipito-parietal encephalocele and normal cranial region." (PMID 31628096, 2019).
gallbladder cancer (5 papers, 2020 to 2024). "In gastric and gallbladder cancers, Nectin-4 activates Ras-related C3 botulinum toxin substrate 1 (Rac1) through the PI3K/AKT pathway, promoting tumor proliferation and metastasis." (PMID 38606099, 2024). "cIAP2 promotes lymph node metastasis of gallbladder cancer by triggering NFκB activation while driving colonic epithelial migration by increasing the abundance and activity of Rac1." (PMID 37391410, 2023).
HIV-1 infection (5 papers, 2014 to 2025). The type species of lentivirus and the etiologic agent of acquired immunodeficiency syndrome (AIDS). "RAC1 activation contributes to HIV-1 induced monocyte-BBB interactions and HIV-1 infection of the brain macrophages." (PMID 36211372, 2022). "Differentiated MDM were infected for 4 h and treated 1 h prior to or 4 h after HIV-1 infection with CT04 (1 μg/ml) and NSC (75 μM), RhoA or Rac1 GTPase inhibitors, respectively." (PMID 26379653, 2015). "Inhibition of both RhoA and Rac1 GTPases resulted in 48 ± 2% decrease in HIV-1 RT activity, when inhibitors were applied prior to HIV-1 infection of MDM, whereas post-infection treatment with Rho GTPase inhibitors led to 85 ± 3% diminution in HIV-1 RT." (PMID 26379653, 2015).
ischemia (5 papers, 2010 to 2022). A hypoperfusion of the BLOOD through an organ or tissue caused by a PATHOLOGIC CONSTRICTION or obstruction of its BLOOD VESSELS, or an absence of BLOOD CIRCULATION. "Knocking out or pharmacological inhibition of Rac1 reduced the degree of brain tissue damage and edema after ischemia." (PMID 34551394, 2021). "Interestingly, inhibition of Rac-1 by NSC23766 attenuated neuronal cell apoptosis in response to ischemia by preventing JNK activation providing a potential explanation for the anti-apoptotic effect of EHT1864." (PMID 24244677, 2013). "There were 10 active constituents against ICVD, including quercetin, luteolin, kaempferol, and naringenin, and 10 important targets for anticerebral ischemia, namely, PIK3CA, APP, PIK3R1, MAPK1, MAPK3, AKT1, PRKCD, Fyn, RAC1, and NF-κB1." (PMID 35432563, 2022). "A PAK1 substrate was used to pull down active, GTP-bound Rac1 via its PBD domain, in order to examine Rac1 activity in total CA1 lysates at 3 h following ischemia/reperfusion." (PMID 20830300, 2010).
lung squamous cell carcinoma (5 papers, 2020 to 2026). "Despite DLBCL, RAC1 expression is also found in various cancers such as breast invasive carcinoma, gastric malignancies, and lung squamous cell carcinoma." (PMID 36552804, 2022).
memory impairment (5 papers, 2017 to 2023). "Rac1 is a crucial protein involved with learning and memory and its hyperactivity is associated with memory impairments through enhanced forgetting." (PMID 35936771, 2022). "Based on these results, Rac1 activation is linked to METH-induced memory impairment in novel object recognition." (PMID 31660086, 2019). "However, whether Rac1 dysregulation is involved in other forms of memory impairments associated with AD is unknown." (PMID 35936771, 2022). "Some studies have demonstrated that the Rac1 inactivation will lead to synaptic plasticity changes and memory impairment." (PMID 38094506, 2023). "For example, DISC1 (Disrupted in Schizophrenia) regulates dendritic spine morphology via Rac1 and mutations in the cofilin kinase PAK3 lead to X-linked mental retardation and memory impairments." (PMID 28912711, 2017). "However, little is known about the effect of Rac1 expressed in the NAc on METH-induced memory impairments." (PMID 31660086, 2019). "Taken together, our findings highlight the roles of Rac1 in the regulation of METH-associated contextual memory and spine plasticity in D1-MSNs, providing a therapeutic target for the treatment of aberrant addiction memory and improvement of drug-induced memory impairment." (PMID 31660086, 2019).
ovarian tumor (5 papers, 2015 to 2024). "Elevated levels of LPA and S1P are both associated with ovarian tumor cell migration, invasion and metastasis and these processes require Rac1-dependent actin remodeling." (PMID 30261690, 2018). "The omentum is a favored ovarian tumor cell niche based on initial chemoattraction by adipocyte secreted factors that can stimulate Stat3-mediated Rac1 activation." (PMID 30261690, 2018). "Inhibition of Rac1 activity or knockdown of Rac1 expression restored epithelial characteristics to ovarian tumor cells and inhibited migration and invasion." (PMID 30261690, 2018). "Experimental evidence demonstrates that elevated Rac1 activity is sufficient to drive aspects of EMT in ovarian tumor cells." (PMID 30261690, 2018). "An inhibitor of Rac1 (NSC23766) decreased ovarian tumor cell migration, invasion and matrix-metalloproteinase production." (PMID 30261690, 2018). "How Rac1 specifically influences ovarian tumor cells within these two separate environments remains to be explored." (PMID 30261690, 2018). "CD44 promotes ovarian tumor cell-peritoneal cell adhesion through binding of its ligand hyaluronan in complex with versican and is generally known to signal through multiple pathways downstream of Rac1 to promote tumor cell invasion." (PMID 30261690, 2018). "Interactions between human omental CAF and ovarian tumor cells also result in an integrin/p38/Rac1-dependent activation of cytokine secretion by CAFs, which in turn promotes tumor cell proliferation and metastasis through activated glycogen breakdown and glycolysis." (PMID 30261690, 2018). "As illustrated in preceding sections, Rac1 plays a critical role in the key processes that impact tumor dissemination and as such, Rac1 may contribute to ovarian tumor cell escape from the peritonium." (PMID 30261690, 2018). "Pharmacologic inhibition of Rac1 decreased S1P-dependent ovarian tumor cell invasion." (PMID 30261690, 2018). "Ligands present in the ovarian TME are likely to activate Rac1 by impinging on ErbB3, ErbB4 and MET receptors, which are expressed in 76–98% of ovarian tumors." (PMID 30261690, 2018). "Pharmacologic inhibition of Rac1 inhibited EGF-stimulated p21-activating kinase (PAK) phosphorylation, filopodia formation and invadopodia in ovarian tumor cell lines indicating contributions of Rac1 in cancer-relevant functions." (PMID 30261690, 2018). "When multiple ovarian tumor cell lines were studied, the ability of LPA to stimulate migration was highly correlated with LPA-dependent Rac1 activation." (PMID 30261690, 2018). "LPA activation of Rac1 has also been reported to be dependent on a Src/p130Cas pathway for ovarian cell migration and the Rac1 GEF βPIX was necessary for LPA-induced invadopodia formation although βPIX knock-down did not disrupt LPA-stimulated migration in certain ovarian tumor cell lines." (PMID 30261690, 2018).
pulmonary hypertension (5 papers, 2012 to 2024). Increased pressure within the pulmonary circulation due to lung or heart disorder. "In our research, the PI3K/AKT/mTOR pathway was activated in pulmonary artery hypertension, and we believe that Rac1 plays an important role in this process." (PMID 35962329, 2022). "Rac1 is also expressed in smooth muscle cells, which contribute to the pathology of pulmonary hypertension (PH), a life-threatening disorder." (PMID 23152932, 2012). "Rac1 is expressed in smooth muscle cells, a critical cell type involved in the pathogenesis of pulmonary hypertension." (PMID 23152932, 2012). "Bcr and Abr play a critical role in down-regulating hypoxia-induced pulmonary hypertension by deactivating Rac1 and, through this, reducing both oxidative stress generated by leukocytes as well as p38 phosphorylation, IL-6 production and proliferation of pulmonary arterial smooth muscle cells." (PMID 23152932, 2012). "A total of 15 patients without pulmonary hypertension (non-PAH), 19 patients with PAH and 25 patients with CTEPH were studied by measuring conventional markers, GTP-related Rap1 levels, RhoA, RalA, Rac1 and Ras in the platelets." (PMID 36984870, 2023).
T cell lymphoma (5 papers, 2018 to 2023). "In adult T-cell leukemia/lymphoma (ATL), RAC1 is activated by the RHO GEF TIAM1 (T-cell lymphoma invasion and metastasis) and regulates the formation of lamellipodia to enhance tumor cell infiltration." (PMID 31248017, 2019). "GEFs facilitate GTP binding on Rac1 by releasing the bound GDP, and several GEFs are shown to govern Rac1 activation including T cell lymphoma invasion and metastasis (Tiam1) and Son of Sevenless 1 (Sos1)." (PMID 34063353, 2021). "A less common bivalent class of gain-of-function (GOF) missense mutations observed in multiple Vav1 domains culminate in Rac1 and NFAT activation, but do not affect Notch inhibition, and are also observed in PTCL, NOS (and other T-cell lymphomas)." (PMID 36845711, 2023). "Both RAC1 and CDC42 play a prominent role in the ALK-driven ALCL, a subtype of T-cell lymphoma." (PMID 31248017, 2019).